CD4 (CD4 molecule)
Diseases named in the same sentence as CD4 in open-access papers (continued):
Sharing a sentence is not in itself a finding about the gene and the disease.
tumor (continued). "In addition, although tumor‐infiltrating CD4+, CD8+, and γδ T cells all showed high expression of IFN‐γ and TNF‐α in both groups with immunotherapy, the frequency of TNF‐α+ γδ T cells was markedly higher when transferred cells were loaded with antigen." (PMID 40091603, 2025). "To clarify the distinct immune activities as characteristic responses of the two states of tumour cells, we performed further dimensionality reduction and clustering on NK and T cells, revealing seven subtypes of CD4 T cells, six subtypes of CD8 T cells and four subtypes of NK cells." (PMID 40292733, 2025). "Similarly, knockout of RBMX significantly increased the proportion of CD4+T cells in immune cells of subcutaneous tumor tissues." (PMID 40941025, 2025). "Firstly, we analyzed the subtypes and differentiation of tumor-infiltrating CD4+ T cells in OC." (PMID 41008548, 2025). "CD4+ T cells and DCs are crucial maintainers of the cycle, while B cells may combat tumor cells via antibody production." (PMID 41030446, 2025). "CTT promotes the differentiation of myeloid-derived suppressor cells (MDSCs) into mature dendritic cells and macrophages, activates antigen-presenting cells and natural killer (NK) cells, and induces Th1-dominant CD4+ T-cell-mediated antitumor immunity in numerous highly metastatic tumor models." (PMID 40959278, 2025). "While ICI therapy generally expands the Th1 population across different tumor types, tissue-specific conditions or variations in the tumor microenvironment may influence the differentiation of CD4+ T cells towards other Th subsets." (PMID 39325360, 2025). "Among these, CD4 + T cells can crucially enhance the body’s anti-tumor immune response." (PMID 40140925, 2025). "The CD4+/CD8+ ratio not only reflects the balance of immune responses but may also reveal the extent of immune evasion in the tumor microenvironment." (PMID 41244913, 2025). "In addition, in situ immunofluorescence staining revealed a decrease in the phosphorylation of the AKT protein in the CD4+ T cells isolated from the tumor tissues of Sora-treated mice." (PMID 39743020, 2025). "Although much of cancer immunotherapy has historically focused on CD8+ cytotoxic T lymphocytes, accumulating evidence highlights CD4+ T cells as central coordinators of both innate and adaptive immune responses, capable of exerting direct and indirect anti-tumor effects." (PMID 40660400, 2025). "Notably, we observed increased infiltration levels of Tregs, a pivotal immunosuppressive CD4+T cell that promote tumour progression, in high‐ALB+KRT7+ EPCs group." (PMID 39834100, 2025). "Another fascinating study on the role of chemokines in recruiting antigen presenting cells revealed that CCL9/CCL21-CCR7 axis enables the entry of naïve CD4+ T cells into the tumour-draining lymph node (TDLNs), while CCL5-CCR5 facilitates their interactions with DCs." (PMID 40852716, 2025). "However, spatial analysis revealed a trend toward better outcomes associated with higher colocalization indices of CD4+ and CD8+ T cells with tumor cells." (PMID 40859352, 2025). "This evidence suggests that while NOS2 and COX2 control the migration of CD8+ T cells, CD4+ T cell mobility is unaffected but could augment TEff function at the tumor margin." (PMID 40663402, 2025). "When comparing mice treated with the TGFβ vaccine to those receiving the vaccine alongside an anti-IL-6R antibody, we found that inhibition of IL-6 signaling reduced overall T-cell infiltration within the tumor, including decreases in CD4+ T cells, CD8+ T cells and regulatory T cells." (PMID 39653766, 2025). "Thus, we sought to apply previously published, validated gene expression signatures to predict tumor-reactive CD4 and CD8 T lymphocytes." (PMID 40848148, 2025). "In addition, Th2 CD4+ T-cells impact the tumor immune microenvironment via the secretion of IL-4, IL-5, IL-13, and IL-17, which exert a pro-tumor growth effect." (PMID 40362529, 2025).
tumor (continued). "An increase in naïve B cells (or their recruitment) together with expansion of activated memory CD4+ T cells may reflect ongoing antigenic stimulation (for example, persistent tumor antigen exposure or chronic inflammation) and a degree of immune activation." (PMID 41333212, 2025). "Notably, there were substantial increases in tumor-infiltrating DCs, NK cells, CD4 + T cells, and CD8 + T cells." (PMID 39743547, 2025). "A reduced CD4/CD8 ratio within tumor tissues is closely associated with tumor progression and immune evasion, accompanied by a marked enhancement of the immunosuppressive phenotype of the tumor microenvironment." (PMID 41170390, 2025). "The higher the infiltration of activated CD4 memory T cells in tumor tissues, the better the prognosis of cancer patients; in contrast, infiltration of resting memory CD4 T cells is associated with poor prognosis, and the abundance of these two cell subsets is significantly negatively correlated." (PMID 40960294, 2025). "However, emerging evidence now highlights that CD4+ T cells can directly engage in tumor cell killing, marking them as potential key players in anti-tumor immunity." (PMID 40177538, 2025). "In support of this notion, RRShigh patients have significantly higher infiltration of immune cells with anti-tumor activity including activated CD4+ T cells, activated CD8+ T cells and immature B cells than RRSlow patients in TCGA cohort, as determined by ssGSEA analysis." (PMID 41001426, 2025). "In contrast, the high-risk group was associated with higher levels of macrophage M0 and CD4 memory-activated T cells, and lower levels of resting dendritic cells and CD4 memory-resting T cells, indicating distinct tumor microenvironment profiles between the groups." (PMID 40697994, 2025). "To investigate whether gM facilitates the activation of CD4+ T cells through modulation of DC, we examined the expression of activation markers on DC within tumor-adjacent lymph nodes." (PMID 40426190, 2025). "Regarding blood tumor burden, patients with SS showed elevated lymphocyte counts (median, 4185 vs. 1060 cells/μl; p = 0.02), CD4+ lymphocytes (median, 2170 vs. 575 cells/μl; p = 0.04), and a trend toward higher CD3+ counts (median, 1765 vs. 784 cells/μl; p = 0.065) compared to patients with eMF." (PMID 40847689, 2025). "Additionally, we investigate how TTN mutations, by altering the TIME, impact the infiltration of CD4 and CD8 T cells, thereby enhancing the activation of anti‐tumour immunity within the body." (PMID 39748197, 2025). "Therefore, increased infiltration of immune cells, such as CD3+ and CD4+ cells, into the tumor microenvironment can improve the survival of cancer patients." (PMID 40236954, 2025). "Thus, mRNA/LNP vaccination promoted the recruitment of antigen presenting cells as well as CD4+ T cells, and acted in synergy with PD-1 blockade to promote an effective anti-tumor immune response." (PMID 41256707, 2025). "Cell superactivator toward DCs, 1‐palmitoyl‐2‐glutaryl phosphatidylcholine (PGPC) adjuvanted with whole‐tumor lysates and lipopolysaccharide, corrects defective migration of senescent DC cells, which also induces differentiation of CD4+ T cells into cytolytic Th1‐CD4+ T cells." (PMID 41427020, 2025). "On the basis of these observations, we speculate that fibroblasts may act as a barrier, hindering the anti-tumor immune capacity of C1QC+RTM/CD4+ T cell pairs." (PMID 40593467, 2025). "Moreover, treatment enhanced tumor infiltration by CD4+ and CD8+ T cells and increased pro-inflammatory cytokines in six patients." (PMID 40805247, 2025). "Additionally, as core effectors of anti-tumor immunity, the activation, migration, and functional states of CD4+ and CD8+ T cells are stringently regulated by the YAP/TAZ pathway." (PMID 41256331, 2025). "CD8 Tex and CD4 Treg mainly act as immunosuppressive in the tumor immune microenvironment." (PMID 40387572, 2025).
tumor (continued). "The low background in normal tissues, except for the kidney (organ of clearance), could facilitate the detection of tumor-infiltrating CD4 + T lymphocytes in tissues that often exhibit a higher background, such as the liver." (PMID 40775564, 2025). "Based on our findings, we propose that HIF-1α may potentiate anti-tumor immune responses through its regulatory role in promoting CD4+ Tcon proliferation and activation." (PMID 41230345, 2025). "Recent reports indicate that CD4 + Tfh cells are tumor-reactive, which may explain their impact on patient survival." (PMID 40287532, 2025). "Target populations were selected for their relevance to anti-tumor immunity (CD8+ T cells, memory CD4+ T cells, and granulocytes), while source populations included vasculature, tumor cells, CAFs, TAMs, and hybrid E/M cells, reflecting key players in tissue architecture and immune regulation." (PMID 40667165, 2025). "Moreover, TXNIP gene expression level was higher in CD4+ T cells originating from blood compared to adjacent normal tissue, and even more compared to tumor samples." (PMID 40260243, 2025). "Furthermore, a recent study demonstrated that Parabacteroides distasonis can support ICI therapy-mediated anti-tumor immunity by stimulating the production of CD4+ and CD8+ T cells within the tumor microenvironment." (PMID 41304278, 2025). "While the proportion of CD4+CD25highCD127low regulatory T cells (Treg) was numerically highest in MPE (6.9% in MPE vs. 3.8% in tumor vs. 4.2% in blood), MPE Tregs possessed lower levels of activation markers (CD69, HLA-DR) and co-inhibitory receptor (PD-1, LAG-3, TIM-3) expression." (PMID 41415427, 2025). "However, the CD4+/CD8+ cell ratio was maintained in all tumor specimens with the percentage of CD4+ cells maintained in 5/8 tumors (P > 0.05) and the percentage of CD8+ cells maintained in 7/8 tumors (P > 0.05)." (PMID 40791544, 2025). "Notably, Th2 cells were able to promote immune escape in the TME while CD4+ Tem exerted anti-tumor effects." (PMID 40801655, 2025). "In this group, only one patient with a stage T1 tumor had a CD4−/CD8+ phenotype." (PMID 40427170, 2025). "Epithelioid mesotheliomas tend to exhibit an immune-excluded phenotype with an abundance of tumor-infiltrating lymphocytes (TILs) in the stromal areas—particularly CD4+ Th1-polarized T cells and B cells—but with fewer T cells making direct contact with tumor islets." (PMID 41463268, 2025). "Thus, CD80 and CD86 are critical for CD4 T cells and for radiation-mediated Treg expansion in the tumor immune environment." (PMID 41417245, 2025). "Moreover, CD4+ T helper cells promote anti-tumor immune responses by stimulating macrophages and DC as well as supporting CD8+ T cell and B cell activation." (PMID 40282480, 2025). "In addition, examining the effects of CD20 upregulation in tumor cells on T‐cell activation demonstrated that the combination of Mosun‐Pola enhanced T‐cell activation markers in both CD4+ and CD8+ T cells during the TDCC reaction." (PMID 41140808, 2025). "To reveal which CD4+ T cell subsets contribute to the allogeneic CD4+ T cell help that supports CD8+ T cell activation, we stimulated a mixture of splenic CD8+ and CD4+ T cells from TC-1 tumor–bearing mice with the E743–77-pulsed mBMDCs of either the WT or bm12 strains." (PMID 40857404, 2025). "Increased frequency of T cells and NK cells in the orthotopic tumor in the Tgm2 knockout mice supported an increase in immune activation, especially with an increase in both the frequency of CD4+ T cells and their elevated expression of the exhaustion markers PD-1 and LAG3." (PMID 40777010, 2025). "The effects of calcitriol on CD3+CD4+ lymphocytes varied depending on mouse age and tumor type." (PMID 40894304, 2025). "Furthermore, the distribution of immune phenotypes showed greater variability across tumor samples for CD8+ TILs compared to CD4+ TILs (p < 0.01 and p = 0.06, respectively)." (PMID 40523956, 2025).
tumor (continued). "Notably, there was a pronounced infiltration of activated T cells—particularly CD4 memory T cells and γδ T cells—as well as M1 macrophages, underscoring an enhanced anti-tumor immune response within this subtype." (PMID 40557143, 2025). "However, in the tumor stroma, only CD4-positive cell density showed a significant correlation with YAP1-positive cell density (r = 0.690, P = 0.008)." (PMID 40051494, 2025). "Furthermore, the combination treatment with TTFields and anti-PD-L1 recruited fewer CD4+ T cells into the tumor center than the combination treatment with TTFields and anti-PD-1." (PMID 40098106, 2025). "However, studies have also shown that certain fibroblast types such as Ccl19+ fibroblasts, can have anti-tumor function potentially by supporting CD4+ T and B/plasma cell function." (PMID 40568084, 2025). "CD4+ T helper cells have a dual role: Th1 cells support antitumor responses and can directly kill tumor cells through cytokine release (IFN-γ and TNF-α), while Th2 cells promote tumor progression by secreting anti-inflammatory mediators, such as IL-4 and IL-13, that suppress immune activity." (PMID 41230456, 2025). "This complements the PD-1+CD8+ T cell findings: together, they paint a clear immune landscape—residual tumor risk is elevated in patients with an “exhausted” immune profile (high PD-1+CD8+ T cells) and reduced in those with an “activated” profile (high CD28+CD4+ T cells)." (PMID 41479903, 2025). "CD4+ T cells are responsible for TSLP-mediated tumor protection in the skin." (PMID 39744942, 2025). "The persistently high proportion of Tregs in CD4+ T cell compartment might explain why CD4 blockade resulted in slight suppression of tumor growth." (PMID 40977690, 2025). "Also, reduced MHC-II expression prevents tumor cells from presenting antigens to CD4+ T-cells, impairing helper T-cell activation and weakening the adaptive immune response." (PMID 40299416, 2025). "Tumor‐infiltrating immune cells were dissociated from tumors and analyzed by flow cytometry, and we found that overexpression of Rfwd3 significantly inhibited infiltration of CD4+ T cells, CD8+ T cells, NK cells, and DCs, and increased MDSCs." (PMID 41117130, 2025). "Furthermore, chronic inflammation within the TME promotes tumor progression, and we observed a decrease in Tregs (CD4+CD25+CD127-), which are known to support tumor growth and suppress anti-tumor immune responses in the PTX+SHP group." (PMID 40094005, 2025). "Therefore, CD4+ T cells play an indispensable role in orchestrating precise anti-tumor immune responses." (PMID 40593467, 2025). "CXCL9/10 attract CD8+ and CD4+ T cells and facilitate their recruitment to tumor sites." (PMID 41332581, 2025). "In tumor immunity, CD4+ T cells exhibit both antitumor and protumor effects." (PMID 40568973, 2025). "In addition, we applied immunofluorescence analysis of CD4 and CD8 to tumor tissue sections, demonstrating a significant suppression of both CD4+ and CD8+ T cells within the TME by stress exposure." (PMID 40670350, 2025). "This alteration may contribute to a more effective and sustained immune response, as the proper differentiation of CD4+ T cell subsets is crucial for maintaining a balanced and potent anti-tumor environment." (PMID 41293181, 2025). "Overall, RPT significantly reduced CD3+ and CD4+ T cells in both tumor models." (PMID 40475779, 2025). "In addition, CD4 T cells are also essential for shaping and enhancing the anti-tumour cytotoxic CD8 response." (PMID 40351814, 2025). "Nevertheless, the potential contribution of NKG2D-expressing CD4+ T cells or helper T cell subpopulation depletion, or other tumor microenvironment factors to the suppression of CD8+ T cell function in B16F10-ULBP2 tumors cannot be ruled out and warrants further investigation." (PMID 40243581, 2025).
tumor (continued). "Approximately 10% of patients with GC receiving PD-1 blockade progress rapidly, to hyper-progressive disease, which is related to Treg cell proliferation in tumor tissue, an increase in immunosuppressive CD4+ T cell subset that hinders effective anti-tumor immunity." (PMID 40438098, 2025). "Mechanistic studies on Foxp3+ Treg-mediated protumor effects reveal their suppression of CD8+ CTL cytotoxicity and enhancement of tumor invasiveness, with elevated Foxp3+/CD8+ and Foxp3+/CD4+ ratios confirmed as independent risk factors for postoperative recurrence." (PMID 40510347, 2025). "Our findings suggest that resistance-associated DEGs such as RAMP1, GSG1L, and GRIK4 may contribute to shaping the tumor microenvironment through interactions with M0/M2 macrophages and resting CD4+ memory T cells." (PMID 41234433, 2025). "We also found that HMGB1, a TLR4 agonist that can induce IL-24, is highly upregulated in calcipotriol-treated tumor cells in a CD4+ T cell–dependent manner, suggesting that it may contribute to IL-24 induction in macrophages." (PMID 39782693, 2025). "Notably, across all cell types tested, majority of T cell-tumor pairings (CD4+ vs. CD8 + ) were found within a radius of 0–15 μm." (PMID 39910335, 2025). "A significant reduction in both CD8+ and CD4+ T cell infiltration was apparent in RAC1A159V tumors, further suggesting a shift toward a cold tumor caused by the RAC1A159V mutation that potentially contributes to the diminished responsiveness to anti-PD1 treatment." (PMID 41160695, 2025). "Although we demonstrate that CD8+ T cells are required for the anti-tumour effects of DR, the Cd4-Cre model used in our study deletes Bdh1 and Oxct1 in both CD4+ and CD8+ T cell lineages; therefore, we cannot exclude a contribution of ketolysis in CD4+ T cells to the observed effects." (PMID 41366157, 2025). "Finally, we show that ALDH1A3-produced atRA works in a paracrine immunoregulatory fashion to promote tumor tolerance through depletion of Th17 CD4 T cells and enhancement of Th2 CD4 T cells." (PMID 41210994, 2025). "High expression of calreticulin promotes intra-tumor infiltration of DC and CD4+ Th1 cells." (PMID 40356601, 2025). "In HCC, Tregs are elevated in tumor tissues and blood, with increased CD4+CD25+ cells." (PMID 40242773, 2025). "Correlation analysis with the tumor microenvironment revealed that the expression of immune cells, such as B cells, endothelial cells, NK cells, plasma, CD4 T cells, CD8 T cells, and macrophages, varied significantly between the high and low UBE2I expression groups." (PMID 40025314, 2025). "By inducing immediate tumor reduction, expanding effector and memory CD4 + and CD8+ T cell populations, and enhancing interferon-gamma and granzyme B activity, it primes the immune system to eliminate residual micrometastatic disease and reduces the risk of recurrence." (PMID 40115081, 2025). "Notably, high tumor differentiation and high expression levels of CD4 and CD8 were significantly correlated with a better prognosis for EC (P < 0.05)." (PMID 40587482, 2025). "Elevations in CD19+ B and CD4+ T cells may facilitate more effective anti-tumor immunity, whereas an increased CD8+ T cell percentage could reflect the activation of immune evasion pathways." (PMID 41244913, 2025). "In the present study, as part of this investigation, multiplex IHC analysis was performed on a small number of patients whose tumours were biopsied, and an increase in CD4+ and CD8+ T cells was observed within the tumour tissues at 3 or 5 weeks after GX-I7 administration." (PMID 40490502, 2025). "Rather, they may function in the presentation of intracellular viral antigens to CD8 and CD4 T cells, thereby increasing T cell mediated tumor control." (PMID 40356924, 2025). "C1QC TAMs are pro-phagocytic and may support anti-tumor immunity through cross presentation to CD4 T cells in the tumor." (PMID 41415295, 2025).